KL (klotho)
Diseases named in the same sentence as KL in open-access papers (continued):
Sharing a sentence is not in itself a finding about the gene and the disease.
tumor (continued). "Furthermore, FGF23 possibly contributes to a bone-like microenvironment in phosphaturic mesenchymal tumor, mixed connective tissue variant (PMTMCT), through FGFR1c/KL, inducing enhanced FGF23 production by the tumor cells and worsening TIO." (PMID 33520985, 2020). "KL is a possible tumor suppressor in urothelial carcinoma of the bladder." (PMID 33520985, 2020). "Considering these data together, it is clear that further efforts are required to ascertain whether circulating Klotho has a role as a serum marker that could aid in the early diagnosis of different tumour types." (PMID 32585905, 2020). "This may, in large part, be due to the fact that KL acts as a tumor suppressor in various types of cancer, whereas such a function is not established for FGF23." (PMID 33520985, 2020). "In addition to being described as a tumour suppressor gene in numerous solid tumours and haematological malignancies, Klotho represents a possible therapeutic target for patients with these diseases, the majority of whom have limited treatment options." (PMID 32585905, 2020). "In addition to functioning as a tumour suppressor in numerous solid tumours and haematological malignancies, Klotho represents a candidate therapeutic target for patients with these diseases, the majority of whom have limited treatment options." (PMID 32585905, 2020). "Furthermore, we examined the effects of klotho on cell proliferation in tumor tissues derived from control and klotho overexpressed mice using anti-PCNA or anti-Ki67 antibody." (PMID 32614356, 2020). "Since it has been shown that bone-forming cells such as osteoblasts and osteocytes express low amounts of Klotho, the Klotho expression in tumor cells may reflect the differentiation of mesenchymal stem cells to osteoblastic lineage cells." (PMID 30627598, 2019). "First, we conclude that the ectopic expression of Klotho in the tumor cells may lead to the activation of FGFRs." (PMID 30627598, 2019). "Second, we conclude that the expression of Klotho in PMTMCTs may reflect the osteoblastic differentiation of tumor cells." (PMID 30627598, 2019). "Klotho silencing in HCC cells via siRNA enhanced tumor cell growth in vitro." (PMID 29799477, 2018). "By enhancing Ca2+-leakage-mediated ER stress, Klotho could increase the calreticulin exposure at the surface of tumor cells and so, facilitate immunogenic cell death." (PMID 30441794, 2018). "Recent studies in cancer demonstrated the KL could be inactivated by promoter hypermethylation and functions as a tumor suppressor." (PMID 29884183, 2018). "KL exerts a tumor suppressive effect mainly through inhibition of IGF-1 signaling." (PMID 30441794, 2018). "Recent studies demonstrated that due to promoter hypermethylation, the expression level of KL was lower in tumor tissues than adjacent normal samples, indicating that KL may function as a tumor suppressor." (PMID 29884183, 2018). "Tumor suppressive effect of Klotho was determined by both in vitro and in vivo studies." (PMID 28153033, 2017). "Studies by re-expression of klotho in cancer cells revealed that sKl acts as a tumor suppressor by inhibiting multiple signaling pathways that include the insulin/IGF-1 pathway, FGF pathway, Wnt signaling pathway, and transforming growth factor-β1 (TGF-β1) pathway." (PMID 29250031, 2017). "Enforced expression of Klotho could significantly induce cell apoptosis and inhibit tumor growth in DLBCL." (PMID 28153033, 2017). "Tumor growth was restrained by administration of Klotho protein in xenograft model of DLBCL." (PMID 28153033, 2017). "Klotho levels were correlated negatively with tumor size in 125 RCC patient samples." (PMID 27999207, 2017). "Moreover, xenograft model treated with either Klotho overexpression vector or recombinant human Klotho administration presented restrained tumor growth and lower Ki67 staining." (PMID 28153033, 2017).
tumor (continued). "Our findings demonstrated that Klotho was a tumor suppressor and modulator of IGF-1R signaling in DLBCL, indicating that targeting Klotho may provide novel therapeutic strategy in DLBCL." (PMID 28153033, 2017). "Being an endogenous circulating hormone, the secreted Klotho could function as an active form and inhibit the tumor growth effectively both in vitro and in vivo." (PMID 28153033, 2017). "In all of these cancers, klotho expression was reduced in tumor tissue compared with normal tissue." (PMID 29250031, 2017). "Recent evidence suggests that KLOTHO functions as a tumor suppressor by inhibiting Wnt signaling." (PMID 30460073, 2017). "If progerin-Apc or klotho-Apc hybrid mice exhibit altered tumour burden compared to Apc mutant mice, one can ask whether treatment of the hybrid mice with rapamycin influences the effects of progerin and klotho on intestinal tumourigenesis." (PMID 25388238, 2015). "Klotho inhibits basal Wnt signalling activity; thus, the protein may function as a tumour suppressor for CRC." (PMID 25388238, 2015). "Further, there was an upregulation of Klotho, a tumor suppressor gene." (PMID 26819566, 2015). "KLOTHO was reported to function as a secreted Wnt antagonist and as a tumor suppressor." (PMID 27844013, 2015). "Notably, KLOTHO promoter hypermethylation was detected in 86% (43/50) tumor tissues and 14% (7/50) adjacent normal tissues." (PMID 27844013, 2015). "Little is known about the serum level of Klotho in HCC and its association with tumor progression." (PMID 23516476, 2013). "The tumor suppressive role of klotho may be initiated by downregulation of IGF-1 receptor phosphorylation, and subsequent decreases in IRS-1, PI3K, Akt, and mTOR phosphorylation." (PMID 23432957, 2013). "Western blot also showed lower klotho protein level in tumor cells than in normal cells." (PMID 23432957, 2013). "Klotho has been demonstrated to function as a tumor suppressor in several tumors." (PMID 23432957, 2013). "Recently, KLOTHO was reported to function as a secreted Wnt antagonist and as a tumor suppressor." (PMID 20482749, 2010). "Recently, published studies suggest that klotho can also serve as a potential tumor suppressor." (PMID 20642846, 2010). "Additionally, in cancer patients, tumor-related factors often modulate Klotho expression." (PMID 39723163, 2024). "The prognostic role of KLOTHO in cancer is starting to be supported by a growing number of studies, and some preliminary findings reported in vivo and in silico suggest that this protein might act as a tumor suppressor with potential prognostic implications." (PMID 39199335, 2024). "Interestingly, KL;ASC tumors exhibited a histotype-selective immune suppressive microenvironment with decreased expression of MHC genes and decreased T-cell infiltration, as well as increased recruitment of CD11b+ GR1+ tumor-associated-neutrophils (TANs)." (PMID 36355420, 2022). "In addition, our results also suggested that Sohlh2 might upregulate Klotho’s expression level by downregulating the expression of DNMT3a and thus functioned as a tumor suppressor in human RCC." (PMID 35127476, 2021). "Klotho may play a role in inhibiting tumour initiation and progression." (PMID 32585905, 2020). "Klotho overexpression could inhibit tumor cell proliferation and induce cell cycle arrest." (PMID 32899868, 2020). "In addition, KLOTHO suppresses the Wnt signaling system and functions as a tumor suppressor." (PMID 30460073, 2017). "Furthermore, we investigated the anti-tumor effect of Klotho on DLBCL xenografts in vivo." (PMID 28153033, 2017). "However, how klotho exerts roles on both the apoptosis and autophagy in tumor cells is unclear." (PMID 23432957, 2013). "Thus, klotho functions as a tumor suppressor by inhibiting apoptosis and autophagy in GC." (PMID 23432957, 2013). "Thus, klotho can serve as a potential tumor suppressor in A549 cells." (PMID 20642846, 2010).
tumor (continued). "Klotho functions as a tumor suppressor in PDAC.Treatment with miR-504 inhibitor and a demethylation agent upregulated Klotho gene expression, while concurrently inhibiting the invasion and migration of BxPC-3 and Panc-1 cells." (PMID 40004457, 2025). "In this cancer, Klotho modulates the IGF-1 and FGF pathways, reducing tumor cell proliferation and enhancing apoptosis." (PMID 40004457, 2025). "Less KL tumor cell proliferation was observed when mice were treated with either HCQ or the combination, which is consistent with the reduced tumor growth." (PMID 36702816, 2023). "Using bulk RNA‐Seq of the KL mice, we showed that TIMP1 expression correlates with a pro‐inflammatory tumour microenvironment." (PMID 37759102, 2023). "Several signal mechanisms have been reported to be involved in the tumor suppressor activity of KL, including the IGF-1, FGF, and Wnt/β-catenin pathways, while the detailed working mode of KL in cancer is still a matter of controversy." (PMID 35468874, 2022). "ASCi.v tumors were highly aggressive, with host mice requiring sacrifice at a median of 40.4 (nude, n=7) and 25 (C57BL/6, n=15) days post-injection, in comparison to the median latency of KL;ASC GEMMs of 79 days post-tumor initiation." (PMID 36355420, 2022). "As expected, qPCR and Western blot analysis of lysates from tumor homogenates showed a decreased expression of AGTR1, increased expression of Klotho, and increased cPARP levels." (PMID 36220392, 2022). "It has been reported that the secreted Klotho protein inhibits TGF-β1/Smad signaling and thus suppresses renal fibrosis and tumor metastasis in mice." (PMID 36232594, 2022). "For instance, it is plausible that the downregulation of 3 upstream regulators of SOD2 (IGFBP7, KL, BTG2), which are potential tumor suppressors, leads to an increase in SOD2 when the malignancy of IPMN worsens." (PMID 32842508, 2020). "In these tumors, spindle-shaped tumor cells, which are considered the principal source of FGF23 in TIO, were positive for Klotho staining." (PMID 30627598, 2019). "Low expression of Klotho, or high expression of CCL2 in patient tumor tissues, correlated with poor overall survival of CRC patients." (PMID 31545552, 2019). "Immunohistochemical staining revealed that both Klotho and CCL2 are expressed primarily in the stroma of the tumor tissue." (PMID 31545552, 2019). "Klotho, an anti-aging and tumor suppressor protein expressed in renal tubular cells, inhibits PI3K/Akt/GSK3β/Snail signaling thus suppressing EMT, tumor invasion and migration." (PMID 26951092, 2016). "This study found that after silencing Klotho gene, p-IGF-1R / p-AKT levels and cell invasion were significantly increased, whereas tumor cell apoptosis was significantly decreased." (PMID 27779100, 2016). "Over 80 publications have studied klotho in a variety of cancer types, with actions including effects on aging, inhibition of IGF-1, FGF2 and TGFβ signaling and tumor suppressor function." (PMID 25944690, 2015). "In order to explore the relationship between the tumor suppressor, Klotho and Wnt/β-catenin signaling pathway, the HepG2 cells were transfected with p CMV6-Klotho and control plasmid p CMV6." (PMID 26499380, 2015). "Immunohistochemical analysis showed that Klotho expression was positively correlated with PAK1 staining (n = 52, r = 0.5427, P<0.0001) in HCC tumor tissues." (PMID 23516476, 2013). "According to our knowledge, most of the studies were devoted to research of Klotho protein expression and mRNA expression in tumor samples, but no work has investigated soluble αKlotho in serum." (PMID 39796185, 2025). "The results indicated that serum Klotho had a negative correlation with cancer but not with tumor-specific death." (PMID 40119098, 2025). "Other genes such as KL, MNX1, HMCN1 and ADCY10 suggest that anoikis resistance is not restricted to survival pathways but also extends to metabolic and proliferative mechanisms that drive both tumour aggressiveness and treatment resistance." (PMID 40830065, 2025).
tumor (continued). "The results showed that co-culture with KL tumor cells significantly increased expression of FAP protein, suggesting that KL tumor cells could activate CAFs." (PMID 38291516, 2024). "Our analysis of tumor RNA-seq data from the mouse AST model (KrasG12D/+; Lkb1fl/fl, KL) showed that multiple epigenetic regulators including LSD1 (lysine-specific histone demethylase 1, also known as KDM1A) were up-regulated in squamous lesions compared to adenomatous lesions." (PMID 37051524, 2023). "Klotho inhibits IGF-1-mediated signaling pathways, which suppress various tumor types." (PMID 37425590, 2023). "We are aware that there may be slight variations in tumor progression between males and females, but for the sake of consistency in the experiments, the same sex was selected for the CDX and KL mouse models." (PMID 37923710, 2023). "It is critical to accurately identify specific tumor subtypes where Klotho is of interest (muscle-invasive versus non-muscle-invasive urothelial carcinoma) to take the most advantage of its potential." (PMID 37958253, 2023). "Four tumor tissues presented high expression of SHANK1, but with low expression of KL." (PMID 35468874, 2022). "In contrast, two tumor tissues presented low expression of SHANK1, but high expression of KL." (PMID 35468874, 2022). "Importantly the accelerated timeframe of tumor development, with a median survival latency of 25 days in C57BL/6 recipients, was less than half that observed for KL;ASC GEMMs." (PMID 36355420, 2022). "The results suggested that treatment of NAC significantly accelerated death and tumor development of KL or KL9 mice but not KL5 mice after tumor induction." (PMID 34369094, 2021). "There were no significant alterations on either the tumor burden or tumor number following Nanog deletion in K, KL, or KP mice compared with control mice (Fig EV2A–C)." (PMID 33439550, 2021). "The result showed that five genes (PRKCA, ADORA1, PPARGC1A, KL, GNG7) could be identified as potentially prognostic factors, and they have also been suggested as tumor suppressor genes." (PMID 31661791, 2019). "Low expression of Klotho, or high expression of CCL2 proteins in tumor tissues, could be correlated with poor overall survival of CRC patients, suggesting that CCL2 represents a promising relevant biomarker and potential target for CRC." (PMID 31545552, 2019). "Tumor cells were not tested in these papers for the major physiological function of klotho to mediate cellular responses to FGF23." (PMID 25944690, 2015). "Bone-metastatic breast and other cancer cell lines often express klotho, but tumor responses to FGF23 have not been reported." (PMID 25944690, 2015). "In this large‐scale population‐based database of NHANES, we explored comprehensively the effect of serum Klotho on cancer, and found regarding pan‐cancer, there was no doubt that serum Klotho exerted a tumor suppressor effect, and a higher level of Klotho concentration had a stronger effect." (PMID 35841322, 2023). "Interestingly, immunohistochemical (IHC) end-point analyses revealed that independent of the tumor source (KL;ASC versus KL;AC), resulting s.c. tumors did not exhibit staining for the AC biomarker nkx2-1." (PMID 36355420, 2022). "In addition, API treatment significantly lowered the percentages of Ki67 staining and the levels of genes and proteins involved in GSH biogenesis in the lung tumors from KL mice but not KL9 mice after tumor induction." (PMID 34369094, 2021). "In addition, reduced tumour growth and decreased cellular proliferation (Ki67) was seen in DLBCL Klotho over-expressing xenograft models, as well as xenografts treated with recombinant human Klotho." (PMID 32585905, 2020).
tumor (continued). "Because Klotho, a tumor suppressor, has inhibitory effects on growth factor receptors such as the fibroblast growth factor receptor (FGFR), IGF-1R, and TGFβ1R, we hypothesized that Klotho would mitigate EGF-induced cell migration in cRCC." (PMID 29928482, 2018). "However, the signaling involved in the tumor suppressive role of klotho protein in GC has not been elucidated." (PMID 23432957, 2013). "Furthermore, research has demonstrated that an overexpression of Klotho negatively regulates the IGF-1 receptor signaling axis, significantly reducing the expression of the proliferation marker Ki-67 and thereby suppressing tumor cell proliferation and invasiveness." (PMID 40427517, 2025). "However, it is not yet clear whether NNMT influences tumor progression by regulating the anti-aging or metabolic pathways mediated by Klotho protein." (PMID 40427517, 2025). "Although circulating Klotho levels may not be altered compared with cancer tissues in all tumour contexts, functional data confirming tumour regression in several in vivo models that are not Klotho deficient supports further evaluation of Klotho as a candidate therapeutic target." (PMID 32585905, 2020). "Furthermore, similar to progerin and klotho, approaches that target mTOR signalling may have beneficial effects on the human lifespan independent of potential effects on tumour formation." (PMID 25388238, 2015). "However, the signaling pathways by which klotho may inhibit GC cell survival and tumor growth have not been reported." (PMID 23432957, 2013). "However, HFD did not rescue tumor number in mice bearing G6pdKO;KL lung tumors, indicating that lower fat availability due to reduced de novo lipogenesis may not affect KL lung tumor initiation, but suppress tumor growth." (PMID 38997257, 2024). "According to some studies, methylation status and reduced KL expression are independent of age, gender, TNM stage, histological grade, or tumor differentiation." (PMID 33520985, 2020). "We highlight the unique capacity of KL;ASC, but not KL;AC, tumor cells to effectively re-colonize the lung in recipient i.v. transplanted mice, with histopathological features, oncogenic signaling profiles and previously characterized therapeutic responses maintained." (PMID 36355420, 2022).